ENSG00000283977 (novel transcript)
Gene: Protein-coding gene on chromosome 11 (6,481,485 to 6,508,978, forward strand). Ensembl gene ENSG00000283977.
Genetic constraint (gnomAD): Missense variants: 165 observed, 136.09 expected, observed/expected ratio (o/e) 1.21, 90% interval 1.07 to 1.38. Synonymous variants: 63 observed, 53.64 expected, observed/expected ratio (o/e) 1.17, 90% interval 0.96 to 1.45.